ASS1 (argininosuccinate synthase 1)
Diseases named in the same sentence as ASS1 in open-access papers (continued):
Sharing a sentence is not in itself a finding about the gene and the disease.
tumor (197 papers, 2010 to 2026). "Arginine deprivation therapy with agents such as pegargiminase has shown improved survival in patients with pleural mesothelioma exhibiting ASS1 loss in tumor cells." (PMID 41300990, 2025). "To evaluate the homogeneity of ASS1 loss, we screened the whole tumor sections when ASS1 loss was confirmed." (PMID 41300990, 2025). "tumor cells are unable to synthesize arginine due to argininosuccinate synthetase 1 (ASS1) deficiency, and instead upregulate insulin-like growth factor 1 (IGF-1R) and enhance ASS1 transcription via c-MYC for arginine metabolic reprogramming." (PMID 39925801, 2025). "Pegargiminase is a pegylated arginine deiminase engineered to treat ASS1-deficient tumors by depleting extracellular arginine and inducing selective tumor cell death." (PMID 41041285, 2025). "To evaluate the homogeneity of ASS1 loss within individual tumors, we conducted staining on whole tumor slides as well as on lymph node metastases and solid organ metastases, where available." (PMID 41300990, 2025). "Arginine deficiency in tumor cells is often linked to the loss of argininosuccinate synthetase 1 (ASS1)." (PMID 40356601, 2025). "Several clinical trials have used a threshold of 50% of ASS1-deficient cells in the tumor as one of the eligibility criteria for ADI-PEG20 treatment." (PMID 39758821, 2025). "ASS-1 catalyses the rate limiting step in arginine biosynthesis, and its loss, a common occurrence in multiple cancers, causes tumours to become reliant on extracellular arginine to survive." (PMID 39516654, 2023). "In renal cell carcinoma, ADI-PEG 20 effectively treated cells with low levels of intracellular ASS1, causing significant growth retardation and prolonged survival in tumor-bearing mice." (PMID 37445845, 2023). "Clinically, the high ASS1/PYCR1 expression was associated with the tumour stage, even in EOC compared to normal tissue samples, and the progression-free survival of OSCC patients." (PMID 36978187, 2023). "We also report ASS1 genetic alteration and their association with tumor prognosis and report differences in ASS1 phosphorylation sites between tumors and control normal tissues." (PMID 38053661, 2023). "Attempts to kill the tumor cells by further depleting arginine with catabolic enzymes proved unsuccessful due to development of resistance caused by upregulation of ASS1." (PMID 35887124, 2022). "ASS1 loss has been associated with an aggressive tumor phenotype, both in preclinical and clinical studies." (PMID 35113813, 2022). "Due to deregulation of ASS1 or ASL (such as loss of ASS1), tumor cells have much a higher demand on extracellular arginine than their normal counter parts, leading to arginine auxotrophy." (PMID 35178349, 2022). "ASS1-expressing tumors recruit certain cells such as tumor-associated macrophages (TAM) and bone marrow-derived suppressor cells (BMDSCs), which can promote immune evasion." (PMID 35265615, 2022). "Administration of ADI‐PEG20 in combination chemotherapy is validated by evidence of potentiation of the cytotoxic effects of folate inhibitors and platinum compounds in ASS1‐deficient tumour cells." (PMID 35466524, 2022). "ASS1 deficiency can redirect aspartate to foster pyrimidine synthesis and promote the proliferation of tumor cells." (PMID 35655758, 2022). "A therapeutic window exists for using arginine‐depleting agents to selectively induce cell death in ASS1‐deficient tumours, whilst maintaining normal cells that replete arginine through endogenous conversion of citrulline." (PMID 35466524, 2022). "Tumors with ASS1 loss fail to mediate the arginine biosynthesis, making these cells to be more reliant on extracellular arginine for tumor survival." (PMID 35910381, 2022). "Termed arginine auxotrophy, ASS1‐deficient tumours depend on the direct uptake of exogenous arginine for growth." (PMID 35466524, 2022).
tumor (continued). "ASS1-deficient tumor cells can spare more cellular aspartate for the biosynthesis of nucleotides and proteins and are dependent on extracellular arginine." (PMID 36319669, 2022). "Tumoral ASS1 loss increases cytosolic aspartate availability for CAD for the synthesis of pyrimidine nucleotides to promote proliferation." (PMID 35910381, 2022). "In patients with ASS1‐deficient malignancies, researchers have observed several adverse clinicopathological features, poor differentiation, increased tumor size, and lymph node involvement, associated with poor prognosis." (PMID 34841717, 2022). "Several clinical trials indicated that this combination treatment has acceptable safety profiles and anti-tumour activity against ASS1-deficient solid tumors." (PMID 35910381, 2022). "ASS1 has been described as the rate-limiting enzyme in arginine resynthesis; thus, arginine depletion has been explored as a strategy in these ASS1-deficient tumours." (PMID 35782058, 2022). "Nevertheless, most treatment strategies for ASS1‐deficient tumors neglect the tumor‐suppressive effect of ASS1." (PMID 35674458, 2022). "Tumours that are deficient in the urea cycle enzyme argininosuccinate synthetase (ASS1) are unable to biosynthesise argininosuccinate derived from citrulline and aspartate and the direct precursor for arginine." (PMID 35466524, 2022). "A growing number of tumour types have been described as arginine auxotrophic, due to variable loss of ASS1." (PMID 35782058, 2022). "ASS1‐deficient tumours exhibit increased proliferation as a result of diversion of aspartate towards enhanced nucleotide synthesis." (PMID 35466524, 2022). "Preclinical studies have demonstrated suppression of both de novo pyrimidine synthesis and the pyrimidine salvage pathway with the combination ADI‐PEG20 and pemetrexed, countering the enhanced pyrimidine synthesis and proliferation of ASS1‐deficient tumours." (PMID 35466524, 2022). "ASS1 is the rate-limiting enzyme in arginine biosynthesis that is deficient in multiple tumor types, resulting in decreased arginine levels." (PMID 35887124, 2022). "These therapeutic strategies exploit a frequent ASS1 deficiency in tumor cells, which renders malignant cells auxotrophic for arginine." (PMID 34037806, 2021). "Although ADI-Peg has demonstrated efficacious anti-tumor activity in ASS1-deficient tumors, such as HCC, ADI-Peg is significantly immunogenic and induces the production of blocking antibodies." (PMID 34037806, 2021). "At any rate, ASS1 deficiency is a selective trait of tumor cells, making arginine deprivation a highly promising therapeutic strategy." (PMID 34298755, 2021). "Arginine synthesis deficiency due to the suppressed expression of ASS1 (argininosuccinate synthetase 1) represents one of the most frequently occurring metabolic defects of tumor cells." (PMID 33664852, 2021). "Modification of ASS1 protein is another important factor that leads to loss of its enzymatic activity and tumor suppressor role." (PMID 33859183, 2021). "Epigenetic silencing or down-regulation of ASS1 expression is one of the major mechanisms contributing to the loss of the tumor suppressor role of ASS1 in cancers." (PMID 33859183, 2021). "Research based on tumour metabolism is focusing on arginine deprivation in argininosuccinate synthase 1 (ASS1) deficient tumours." (PMID 32156681, 2020). "In this study, we found that low ASS1 expression was associated with worse overall survival and higher tumor grade on a large and well-annotated tissue microarray of 138 early stage PDACs that underwent surgical resection at our institution." (PMID 31903153, 2020). "Downregulation of ASS1 caused by promoter methylation increases the susceptibility of tumor cells to PEGylated arginine deiminase (ADI-PEG20), a drug for arginine-deprivation treatment that has been used in clinical trials for a variety of tumors." (PMID 33511116, 2020).
tumor (continued). "ASS1 downregulation has been reported to be associated with advanced tumor stage, high local recurrence rate, and poor relapse- and metastasis-free survival." (PMID 33511116, 2020). "Arginine depletion has another detrimental effect on the anti-tumor activity of the immune system, as ASS1 upregulation causes increased programmed death-ligand 1 (PD-L1) expression, which is a negative regulator of T cells." (PMID 35582579, 2019). "Arginine deaminase (ADI) represents a tool to deplete ASS1-deficient cells of arginine: a pegylated form of ADI (ADI-PEG) was used to deplete ASS1-deficient tumor cells of arginine." (PMID 30813354, 2019). "In osteosarcoma patients, lower ASS1 expression levels in tumor samples were associated with resistance to doxorubicin treatment and with the development of pulmonary metastases." (PMID 30082427, 2018). "ASS1 expression is known to vary across different tumor types and both its loss of expression and overexpression has been shown to influence the effects of therapy." (PMID 29731978, 2018). "Arginine deiminase catalyzes the conversion of arginine to citrulline, thereby depleting the former in ASS1-deficient tumor cells." (PMID 28388291, 2017). "Our findings suggest that ASS1 levels in each tumor cell are associated with invasion capability in response to arginine within the tumor microenvironment through mTORC1 signal regulation." (PMID 28358054, 2017). "ADI-PEG 20 can inhibit cell proliferation in vitro and tumor growth in vivo and is being investigated in clinical trials for ASS1-deficient tumors." (PMID 28938609, 2017). "There was uniform upregulation of this gene cluster (which included Adc, Nos2, Ass1, Gch1, Asl and Got1) in both tumor-associated MP and MG and Gr1+ cells." (PMID 27936099, 2016). "We additionally assessed the effect of ADI-PEG20 on ASS1-deficient UMUC3 xenografts to compare the effects in ASS1-proficient and deficient tumours." (PMID 26972697, 2016). "In this situation, the ASS1-deficient tumor is vulnerable to strategies that target this lifeline; accordingly, treatments to degrade extracellular arginine are being used in the patients with ASS1-deficient tumors." (PMID 26982031, 2016). "We propose that ASS1 deficiency contributes to a more aggressive tumor biology, which may explain its higher prevalence in younger patients." (PMID 41300990, 2025). "This could imply that ASS1 loss or low ASS1 expression could be developed by tumor cells during neoadjuvant therapy, possibly as a therapy escape mechanism." (PMID 41300990, 2025). "Studies have shown that the antitumour activity of ADI-PEG20 is correlated with ASS1 deficiency in tumours, and its therapeutic effect may be eliminated when ASS1 is restored." (PMID 39051546, 2024). "ASS1 is an indicator of arginine depletion, and extracellular arginine depletion causes the polarization of macrophages toward the M2 type, which plays an immunosuppressive role in assisting tumor invasion." (PMID 37366304, 2023). "Conversely, ASS1 tumor positivity was associated with drug resistance and tumor progression." (PMID 37445845, 2023). "ASS1-deficient tumor cells cannot synthesize arginine and may benefit from arginine depletion therapy." (PMID 38053661, 2023). "Indeed, our study validated that the high expression of ASS1 caused by the knockdown of PGAM1 reduced the proliferation of tumor cells in vitro, and alleviated tumor growth in xenograft models." (PMID 35674458, 2022). "Moreover, low ASS1 expression levels in tumor tissues are associated with unfavorable clinical outcomes in a wide variety of malignancies." (PMID 35910381, 2022). "Moreover, arginine deprivation with pegylated arginine deiminase (ADI‐PEG20; ADI; pegargiminase) disrupts thymidine pools and potentiates antifolate cytotoxicity in preclinical ASS1‐deficient tumor models." (PMID 34382365, 2021).
tumor (continued). "One of the most frequently observed metabolic deficiencies of tumor cells is the diminished ability to synthesize arginine due to the suppressed expression of ASS1 (argininosuccinate synthetase 1), rendering these cells arginine-auxotrophic or dependent on exogenous arginine for survival." (PMID 33664852, 2021). "The mechanism underlying ASS1-mediated tumor suppression was investigated in HCC spheroids." (PMID 33838671, 2021). "Reduced ASS1 expression is associated with aggressive tumor phenotypes 13-15." (PMID 31903153, 2020). "Importantly, we found the expression of ASS1 was negatively linked to the tumor stage with less ASS1 expression during tumor progression." (PMID 31000693, 2019). "This hypothesis, however, is only meaningful when majority of the tumor cells expressing deficient/low ASS1." (PMID 28187218, 2017). "The negative prognostic impact associated with deficient ASS1 might be attributed to the newly identified tumor suppressor function of ASS1 besides its functions in arginine metabolism." (PMID 28187218, 2017). "Thus, while ASS1 deficiency is undoubtedly of interest in this tumor, ASS1 overexpression also merits attention." (PMID 26982031, 2016). "ADI-PEG20 is in clinical trials for use in patients with ASS1-deficient tumours." (PMID 26972697, 2016). "On the other hand, we have found ASS1 upregulated in 3D spheroids and tumor samples and we hypothesized that it could be associated with increased chemoresistance (multicellular resistance)." (PMID 26982031, 2016). "Furthermore, several groups have observed that reduced expression of ASS1 is significantly associated with advanced tumor stage and an association with a worse clinical outcome." (PMID 25164070, 2014). "While the detailed cell killing mechanisms may vary among different cell types (see next section), ADI effectively inhibits the growth and survival of ASS1-low tumor cells, and in those cases tested, the susceptibility to ADI is inversely correlated with the level of ASS1." (PMID 34298755, 2021). "Therefore, we tested the hypothesis that targeting essential arginine would benefit patients with non‐squamous NSCLC characterized by loss of the ASS1 tumor suppressor." (PMID 34382365, 2021). "However, some tumor cells are deficient in ASS1, which can result in arginine auxotrophy." (PMID 32353864, 2020). "Moreover, ASS1 deficient GBM have a worse prognosis compared to ASS1 positive tumours." (PMID 29422017, 2018). "Thus, ADI-PEG20 may be useful in the clinic to target therapy-resistant hypoxic cells in ASS1-proficient tumours and ASS1-deficient tumours." (PMID 26972697, 2016). "As the induction of autophagy in response to arginine deprivation may have a pro-survival role in patients with ASS1-deficient sarcomas, the combination of arginine deprivation therapy with autophagy modulators might potentiate anti-tumor effects in patients with drug-resistant sarcomas." (PMID 27683125, 2016). "We included the following factors: sex, patient age, Clavien-Dindo classification, pathological tumor status, pathological lymph node status, lymph vessel infiltration, blood vessel infiltration, and ASS1 expression." (PMID 41300990, 2025). "Three groups of tumor cells were used in the fluorescence double reporter assay, and Rbfox3 binding to the Ass1 promoter was unaffected in the treated group." (PMID 39777898, 2025). "Following the downregulation of ASS1, tumor cells rely on an external arginine delivery–a potential “Achilles heel” of these tumors." (PMID 41300990, 2025). "This not only identifies ASS1 as a core target of EVO in regulating arginine metabolism but also demonstrates that the combination of EVO and targeted ASS1 inhibition can enhance anti-tumor effects by synergistically reducing arginine synthesis." (PMID 41304979, 2025).
tumor (continued). "On the other hand, comparison of primary (kidney) and clonally related lung metastases revealed upregulated ASS1 expression in the metastatic cell lines relative to their primary tumor-derived counterparts." (PMID 39920310, 2025). "A major determinant of tumor arginine dependence is the expression of argininosuccinate synthase 1 (ASS1), the enzyme required for endogenous arginine biosynthesis." (PMID 41511309, 2025). "To further limit arginine supply, we combined systemic arginine depletion with tumor-intrinsic suppression of de novo synthesis by implanting 4T1 cells with knockdown (KD) of ASS1(ASS1-KD) into AFD-fed mice." (PMID 41511309, 2025). "In particular, ASS1 suppression leads to arginine autotrophy that enhances tumor cell migration, invasion and metastasis." (PMID 40025169, 2025). "Tumor cells often evade de novo arginine synthesis by silencing ASS1/ASL, thereby becoming dependent on exogenous arginine." (PMID 40535116, 2025). "We established an O.E. Rbfox3‐B16 cells tumor‐bearing mice model, and immunohistochemical staining of O.E. Rbfox3 tumor tissues revealed suppressed Ass1 expression in tumors with high Rbfox3 expression." (PMID 39777898, 2025). "After induction with LPS, tumor cells highly express the transcription factor Rbfox3 and transcriptionally repress argininosuccinate synthase 1 (Ass1) expression in a phase‐separated manner, promoting the transformation of tumor cells into MLTCs." (PMID 39777898, 2025). "Although previous literature has suggested a tumor suppressive role for ASS1, we confirmed a direct correlation between high ASS1 and poor OS in the GSE25066 dataset, and others have confirmed this in the TCGA BRCA dataset." (PMID 40645971, 2025). "Strikingly, silencing ASS1 or ASL to suppress de novo arginine synthesis in the primary tumor promoted metastasis." (PMID 39920310, 2025). "Arginine metabolism demonstrates significant potential in tumor immunoregulation, particularly through ASS1 downregulation-mediated arginine deprivation therapy (ADT) and its impact on T cell function as well as the expansion of MDSCs and Tregs." (PMID 40666095, 2025). "Despite these limitations, immunohistochemistry remains the gold standard for detecting ASS1 protein in the tumor cells, as supported by previous clinical studies investigating arginine deprivation therapy." (PMID 41300990, 2025). "Using the Cell Signaling antibody, we subsequently performed ASS1 immunohistochemical staining on whole tumor sections from 97 patients (and corresponding metastases in ASS1-loss tumors)." (PMID 41300990, 2025). "In diverse human tumor cell lines, ASS1 (argininosuccinate synthase 1) expression is lost, preventing the tumor from regenerating methionine via homocysteine, thereby creating a “methionine auxotrophic” phenotype." (PMID 41293169, 2025). "Western blotting analysis of tumor tissues found that EVO remarkably reduced the expression levels of proteins β-catenin, c-MYC, Cyclin D1, and ASS1 in subcutaneous CRC syngeneic tumor allografts." (PMID 41304979, 2025). "Biomarkers such as arginase-1 (ARG1) and argininosuccinate synthase 1 (ASS1) are differentially expressed and contribute to immunosuppressive tumor microenvironments, offering insight into immune evasion mechanisms." (PMID 41244835, 2025). "More recently, it has been shown that ASS1-independent tumor resistance to ADI-PEG20 can rely on macropinocytosis of extracellular vesicles that are degraded and recycled to supply arginine." (PMID 39758821, 2025). "This therapy option is also biomarker-supported via the detection of ASS1 expression in the tumor cells." (PMID 41300990, 2025).